GSTT2 (glutathione S-transferase theta 2 (gene/pseudogene))
Description:
Conjugation of reduced glutathione to a wide number of exogenous and endogenous hydrophobic electrophiles. Has a sulfatase activity.
Target class: Enzyme; Transferase
Gene: Protein-coding gene on chromosome 22 (23,980,058 to 23,983,915, forward strand). Ensembl gene ENSG00000099984.
Subcellular location: Cytoplasm, cytosol; Nucleus
Subcellular location (Human Protein Atlas): Cytosol; Nucleoplasm
Homologues: Orthologues: macaque GSTT2B (89% identical), mouse Gstt2 (77% identical), rat Gstt2 (61% identical), zebrafish gstt2 (36% identical), Drosophila melanogaster GstT3 (30% identical), Drosophila melanogaster GstT1 (28% identical), Drosophila melanogaster GstE12 (27% identical), Drosophila melanogaster GstE2 (26% identical), Drosophila melanogaster GstT2 (25% identical), Drosophila melanogaster GstE1 (25% identical), Drosophila melanogaster GstE6 (25% identical), Drosophila melanogaster GstE3 (24% identical), and 33 more. Paralogues in human: GSTT2B (99% identical), GSTT4 (42% identical), EEF1G (27% identical), GDAP1 (25% identical), CLIC1 (21% identical), CLIC4 (21% identical), CLIC6 (21% identical), GDAP1L1 (21% identical), CLIC5 (20% identical), CLIC3 (20% identical), CLIC2 (19% identical), GSTZ1 (18% identical), and 2 more.
Diseases named in the same sentence as GSTT2 in open-access papers:
GSTT2 is named in the same sentence as 14 diseases in open-access papers, as found by Europe PMC text mining. Sharing a sentence is not in itself a finding about the gene and the disease. The quoted sentences say what the papers report.
Bladder Cancer (2 papers, 2024). "Ankfn1, Gstt2, Plec, Gphn, Fmo5, Cmss1, Ahnak, Mecom, Slc2a1, Gsta4, Kras, Peak1, and Hmga2 were associated with worse disease-free survival in bladder cancer patients." (PMID 39769061, 2024). "Gstt2, Gphn, Plec Cmss1, Ahnak, Slc2a1, Gsta4, Kras, Peak1, and Hmga2 were associated with worse overall survival in bladder cancer patients, and the association was significant for Gstt2 and Ahnak." (PMID 39769061, 2024). "An 11-gene signature (Hmga2, Peak 1, Kras, Slc2a1, Ankfn1, Ahnak, Cmss1, Fmo5, Gphn, Plec, Gstt2) had the most substantial impact on disease-free survival in bladder cancer patients." (PMID 39769061, 2024). "The impact of GSTT2B and GSTT1 deletions and selected GSTT2 promoter SNPs on the development of bladder cancer and the response of bladder cancer patients to BCG immunotherapy were determined." (PMID 39201633, 2024). "Our screening of the TCGA database revealed that GSTT2 expression in bladder cancer tissues is variable, consistent with our results." (PMID 39201633, 2024). "Recently, the BCG stimulation of bladder cancer cell lines was found to increase the expression of glutathione-S-transferase theta 2 (Gstt2), a member of the glutathione-S-transferase (GST) family." (PMID 39769061, 2024). "In vitro, GSTT2 overexpression in bladder cancer cells decreased intracellular BCG survival." (PMID 39201633, 2024). "Thus, we hypothesised that GSTT2 modulates either the development of bladder cancer and/or the response to BCG immunotherapy." (PMID 39201633, 2024). "Gstt2 WT and KO C57BL/6J mice were orthotopically implanted with the murine bladder cancer cell line MB49-PSA." (PMID 39769061, 2024). "Here, we have identified a gene, GSTT2, responsible for intracellular BCG survival and ROS regulation in the BCG immunotherapy of bladder cancer." (PMID 39201633, 2024). "The combination of Gstt2 and Ahnak significantly influenced overall survival in bladder cancer patients with non-papillary tumors (p-value = 0.025)." (PMID 39769061, 2024). "We previously screened human bladder cancer cell lines for upregulated genes after a two-hour exposure to BCG to identify more predictive markers and found the glutathione-S-transferase theta 2 (GSTT2) gene." (PMID 39201633, 2024). "Finally, we interrogated the Cancer Genome Atlas (TCGA) database to determine if the genes identified in the murine tumor model correlated with outcomes, such as disease-free survival or overall survival in human bladder cancer patients with and without Gstt2 expression." (PMID 39769061, 2024). "Our results indicated that GSTT2, but not GSTT1, modulated the response to BCG immunotherapy in our population, and neither gene impacted the development of bladder cancer." (PMID 39201633, 2024).
colon cancer (2 papers, 2019 to 2024). "GSTT2 expression is associated with a reduced risk of colon cancer, oesophageal squamous cell carcinoma, and Barrett’s oesophagus." (PMID 39201633, 2024). "Promoter SNPs in GSTT2 have been associated with colon cancer risk in the Korean population." (PMID 39201633, 2024). "In the literature, GSTT2 promoter SNP -537G has exhibited better transcriptional factor binding and protection against colon cancer development." (PMID 39201633, 2024).
bladder tumor (1 paper, 2024). "The loss of Gstt2 expression resulted in marked changes in the local bladder tumor environment in response to BCG therapy." (PMID 39769061, 2024).
breast carcinoma (1 paper, 2017). "Previously reported race and survival-associated genes including MUC1, GSTT2, PSPHL, SQLE, and TYMS were associated with race in this population-based study of women diagnosed with breast cancer." (PMID 29228969, 2017). "Specifically, we sought to estimate differences in the expression of two suspected good prognosis genes (ACOX2 and MUC1) and six suspected poor prognosis genes (FAM177A1, GSTT2, PSPH, PSPHL, SQLE, and TYMS) by race, and to examine their associations with risk of breast cancer recurrence." (PMID 29228969, 2017).
colorectal cancer (1 paper, 2007). A primary or metastatic malignant neoplasm that affects the colon or rectum. "Our results collectively suggest that SNPs and haplotypes of the GSTT2 promoter region are associated with colorectal cancer risk in the Korean population." (PMID 17250773, 2007). "In the present study, we sought to determine whether GSTT2 promoter single nucleotide polymorphisms (SNPs) are associated with colorectal cancer risk." (PMID 17250773, 2007). "A total of 436 colorectal cancer patients and 568 healthy controls were genotyped for three GSTT2 promoter SNPs (-537G>A, -277T>C and -158G>A), using real-time TaqMan assay and direct sequencing." (PMID 17250773, 2007).
heart failure (1 paper, 2021). Inability of the heart to pump blood at an adequate rate to meet tissue metabolic requirements. "Haas and colleagues reported decreased expression of Gstt1 and Gstt2 in a mouse model following transverse aortic constriction-induced heart failure and suggest that these genes are involved in adaptive or maladaptive cascades of the failing heart." (PMID 33801838, 2021).
juvenile arthritis (1 paper, 2020). "Previously, MIF was reported in association with susceptibility to juvenile arthritis, GSTT2 with S-phenylmercapturic acid levels in smokers, and USP2 suggestively with urate levels." (PMID 33137956, 2020).
prostate carcinoma (1 paper, 2020). A carcinoma that arises from epithelial cells of the prostate gland. "The POU1F1-derived tumors have 499 exclusive proteins that participate in events such as Platinum drug resistance (AKT3, BCL2 and GSTT2) and Prostate cancer (FGFR1, IGF1R and PDGFD) among others." (PMID 33261069, 2020).
type 2 diabetes mellitus (1 paper, 2015). A type of diabetes mellitus that is characterized by insulin resistance or desensitization and increased blood glucose levels. "Eleven genes in the Glutathione metabolism pathway (Gpx7, Gss, Gsta3, Gstm2, Gstm5, Gstm7, Gsto1, Gstp1, Gstt1, Gstt2 and Mgst2) were observed in type 2 diabetes mellitus." (PMID 25788156, 2015).
cancer (8 papers, 2007 to 2024). A tumor composed of atypical neoplastic, often pleomorphic cells that invade other tissues. "While several studies have reported associations between GSTT2 and differential cancer susceptibility, the potential role of this gene is still unclear due to the structural complexity of this locus in humans." (PMID 26829228, 2016). "In this context, it is possible that the reduced GSTT2 activity caused by the GSTT2B deletion may protect individuals from cancer." (PMID 22216261, 2011). "Based on our mRNA analysis of the cancer cell lines, we expected that low GSTT2 expression would correlate with the GSTT2BFL/Del and GSTT2BDel/Del genotypes." (PMID 39201633, 2024). "To date, no case-control analysis of GSTT2 promoter polymorphisms has been performed in human cancers." (PMID 17250773, 2007). "Thus, GSTT2 activity is important for the protection of cells against toxic products of oxygen and lipid peroxidation, which represents a major source of endogenous DNA damage in humans that contributes significantly to cancer and other genetic diseases." (PMID 17250773, 2007). "In comparison with the hypermethylation of the GSTT2 CpG island, consisting of six CpGs, in the A549, MCF7, and EFO27 cancer cell lines, the patient’s sample was hypomethylated similar to the matched control sample 0N7 and the FancD1 fibroblast line." (PMID 32577795, 2020). "Our data collectively suggest that GSTT2 promoter polymorphisms are involved in CRC development, and it would thus be beneficial to include GSTT2 promoter SNPs when screening for relationships between GST families and human cancers." (PMID 17250773, 2007). "Analysis of methylation levels of THSD1 and GSTT2 genes which were detected in duplicated regions and are frequently aberrantly methylated in cancer showed no changes in patient’s fibroblasts." (PMID 32577795, 2020). "Consistent with the results from cancer cell lines, GSTT2 expression was strong in a fibroblast homozygous for the non-deletion allele, was weaker but detectable when heterozygous, and was undetectable in cell lines homozygous for the GSTT2B deletion." (PMID 19424424, 2009).
tumor (4 papers, 2020 to 2024). "This study aims to dissect the impact of Gstt2 expression on the response to BCG immunotherapy in tumor-bearing bladders." (PMID 39769061, 2024). "In contrast, Gstt2 KO bladders expressed genes involved in inflammation, immune activation, and tumor suppression." (PMID 39769061, 2024). "Both tumor cell types are more enriched in the Gstt2 KO than in the WT bladder." (PMID 39769061, 2024). "The WT Gstt2 bladder environment was characterized by elevated PD-L1 expression, which could be attributed to various cell types (tumor cells, M2 macrophages, and matrix-remodeling fibroblasts) expressing PD-L1-associated genes." (PMID 39769061, 2024). "Indeed, other polyphenolic compounds, such as luteolin and quercetin, have been reported to activate the expressions of glutathione S-transferases, Gsta1 and Gstt2, and decrease the levels of reduced glutathione in LC540 tumor Leydig cells." (PMID 35723385, 2021). "In our two analyzed gene loci (THSD1 and GSTT2), no aberrant methylation in patients was detected in contrast to hypermethylation in the analyzed tumor cell lines." (PMID 32577795, 2020).
neurological disorders (1 paper, 2020). "The messenger RNA expression of GSTT2 was reported as being associated with Charcot–Marie–Tooth disease, which is one of the most common inherited neurological disorders." (PMID 33137956, 2020).
GSTT2 also shares sentences with these, for which no sentence is quoted: breast tumors (1 paper); infection (1).